ZNF221 (zinc finger protein 221)
Description:
May be involved in transcriptional regulation.
Tractability: PROTAC: ubiquitination databases record sites on it.
Gene: Protein-coding gene on chromosome 19 (43,951,204 to 43,967,709, forward strand). Ensembl gene ENSG00000159905.
Subcellular location: Nucleus
Subcellular location (Human Protein Atlas): Nuclear bodies
Pathways (Reactome):
Gene expression (Transcription): Generic Transcription Pathway
Gene Ontology:
Molecular function: protein binding; DNA-binding transcription factor activity, RNA polymerase II-specific; RNA polymerase II cis-regulatory region sequence-specific DNA binding; DNA-binding transcription repressor activity, RNA polymerase II-specific; sequence-specific double-stranded DNA binding
Biological process: regulation of DNA-templated transcription; negative regulation of transcription by RNA polymerase II; regulation of transcription by RNA polymerase II
Cellular component: nucleus; nucleoplasm
Genetic constraint (gnomAD): Loss-of-function variants: 9 observed, 12.34 expected, observed/expected ratio (o/e) 0.73, 90% interval 0.44 to 1.27. The upper end of that interval is the gene's LOEUF score, 1.27, which puts it in group 5 of 6, group 1 being the genes least tolerant of losing a copy. Missense variants: 586 observed, 679.03 expected, observed/expected ratio (o/e) 0.86, 90% interval 0.81 to 0.92. Synonymous variants: 209 observed, 233.58 expected, observed/expected ratio (o/e) 0.89, 90% interval 0.8 to 1.
Homologues: Orthologues: chimpanzee ZNF221 (97% identical), macaque ZNF221 (94% identical). Paralogues in human: ZNF224 (78% identical), ZNF225 (72% identical), ZNF284 (58% identical), ZNF227 (45% identical), ZNF235 (45% identical), ZNF226 (43% identical), ZNF229 (42% identical), ZNF28 (41% identical), ZNF726 (41% identical), ZNF595 (41% identical), ZNF112 (41% identical), ZNF234 (41% identical), and 164 more.
Diseases named in the same sentence as ZNF221 in open-access papers:
ZNF221 is named in the same sentence as 1 disease in open-access papers, as found by Europe PMC text mining. Sharing a sentence is not in itself a finding about the gene and the disease.
ZNF221 shares sentences with these, for which no sentence is quoted: tumor (1 paper).